KRAS (KRas proto-oncogene, GTPase)
Diseases named in the same sentence as KRAS in open-access papers (continued):
Sharing a sentence is not in itself a finding about the gene and the disease.
cancer (continued). "KRAS (Kirsten rat sarcoma virus) is an oncogene that is mutated in about 25% of all cancers, but it only recently became a promising therapeutic target for anti-cancer therapy because of significant scientific breakthroughs." (PMID 39720730, 2024). "While regulators of the MAPKC, such as EGFR and KRAS, are commonly altered in cancer, mutations of MAPKs are rarely observed in cancer patients." (PMID 39062063, 2024). "KRAS, the most frequently mutated oncogene in human cancers, generates two isoforms—KRAS4a and KRAS4b—through alternative splicing." (PMID 39767561, 2024). "Recent studies have shown that KRAS mutations play a crucial role in the metabolic reprogramming of cancer cells, steering them toward an anabolic metabolism essential for biomass production and supporting unconstrained proliferation." (PMID 39682132, 2024). "KRAS is a proto-oncogene that, when mutated, plays a crucial role in the development of various cancers, including colon cancer." (PMID 38195537, 2024). "The frequency of KRAS mutations is variable across different cancer types, with mutation rates up to 88% in pancreatic ductal adenocarcinoma (PDAC), 45–50% in colorectal cancer (CRC) and 30–35% in lung adenocarcinoma." (PMID 38261067, 2024). "TGM2 interacts with multiple factors in the KRAS pathway and is associated with the aggregation of KRAS mutant-induced cancer development." (PMID 39115570, 2024). "Oncogenic signaling, including the PI3K/mTOR pathway and cancer-associated KRAS mutant, markedly elevates SG formation to enhance cancer cell fitness." (PMID 38731625, 2024). "Through in silico analysis and scRNA-seq, we found that the JAG, DLL, and NOTCH families were significantly associated with cancer signatures, including hypoxia, angiogenesis, and KRAS signaling up." (PMID 39074091, 2024). "In the UK cancer network study, it was observed that G12C and G12V variants, both, had poorer median OS compared to the wild-type KRAS (24.9 versus 35.1 months) among metastatic and recurrent CRC patients." (PMID 39056802, 2024). "This indicates that besides addressing the KRAS mutation, other information is necessary in the clinical management of cancer." (PMID 39056802, 2024). "Several HSP40 family members are highly expressed in various types of human cancer, including colorectal, gastric, and KRAS-mutated lung cancers." (PMID 39850800, 2024). "Neoepitopes for 14 of 36 cancer neoantigens were detected in the context of only one HLA allele, and, of the cancer neoantigens that presented epitopes across multiple alleles, nine were KRAS G12X or G13X mutations." (PMID 37857725, 2024). "In both the control and cancer patients, there were positive correlations (p < 0.0001) between KRAS mutational status and the expression of MAP1LC3B, ATG5, ATG10, ATG13, and ATG14." (PMID 39057088, 2024). "Cancer subtypes with G12/13 prevalence in the concordantly upregulated axes are characterized by mutations of the KRAS, PIK3CA, and MLLT3 oncogenes." (PMID 38723607, 2024). "Since the initial discovery that KRAS is mutated in human cancers, there has been intense research efforts to develop targeted anti-KRAS therapies." (PMID 38800401, 2024). "Clinical trials exploring treatments for EGFR- or KRAS-mutated (EGFRmut or KRASmut) cancers have focused on small-molecule inhibitors targeting the driver mutations." (PMID 38639476, 2024). "In a mouse model of PDA, KRAS mutation increased the surface expression of IL-4R197, increasing the vulnerability of cancer cells to cytokines produced by TH2 cells." (PMID 38481800, 2024). "Among the three human RAS genes, KRAS, NRAS, and HRAS, the KRAS gene exhibits the highest mutation rate, reaching about 18% across all human cancers (Catalogue of Somatic Mutations in Cancer (COSMIC), v98)." (PMID 38796063, 2024).
cancer (continued). "To demonstrate this, we examined IC50 (half maximal inhibitory concentration) levels of LUAD cell lines to EGFR inhibitors with respect to the mutational status of EGFR and KRAS as obtained in GDSC (Genomics of Drug Sensitivity in Cancer)." (PMID 39160568, 2024). "A novel transcriptional signature, RAS84, has been developed to identify cancers that are driven by RAS signaling by non-KRAS mutations." (PMID 39682179, 2024). "KRAS is the most frequently mutated oncogene in pan-cancer, and the position 12 glycine is the mutation hot spot." (PMID 38554155, 2024). "Codons 12, 13, and 61 are frequently the sites of cancer-promoting KRAS mutations, with G12 accounting for the majority of these mutations (89%)." (PMID 38794122, 2024). "A ground-breaking inhibitor of KRAS, sotorasib, was approved in 2021 by the U.S. Food and Drug Administration for certain cancers harboring a KRAS G12C mutation." (PMID 38802657, 2024). "There are many different KRAS mutations found in cancer patients, including G12D (33.7%), G12V (32.7%), G12C (14%), and G13D (12.5%)." (PMID 39057088, 2024). "Currently, these pathologies are mainly linked to the nervous system or to cancers driven by the KRAS oncogene." (PMID 39390257, 2024). "For decades, pervasive dogma in the field was that all mutations in all three cancer-relevant RAS isoforms (KRAS, HRAS, and NRAS) were functionally equivalent." (PMID 38800401, 2024). "Further analysis using more cell lines with and without KRAS mutations will help to establish the role of hyperactive KRAS in the response of cancer cells to PCAIs’ effects on AKT phosphorylation." (PMID 38540084, 2024). "In cancer, and particularly in the presence of oncogenic KRAS mutations, in vivo studies concluded that SG increase the resistance of cancer cells to stress." (PMID 39390257, 2024). "Neoantigens derived from somatic mutations in KRAS represent promising targets for cancer immunotherapy." (PMID 38684865, 2024). "GDC-6036 (divarasib) is being evaluated in a Phase Ia/Ib study as a single agent and in combination with other anti-cancer therapies in advanced solid tumors with KRAS-G12C mutation." (PMID 39164274, 2024). "The Kirsten rat sarcoma viral proto-oncogene (KRAS) is a gene that is frequently mutated in human cancers." (PMID 38542866, 2024). "In some cancer cells with mutated KRAS it was found that its suppression causes polyubiquitination and proteasomal degradation of the MYC protein." (PMID 39457457, 2024). "KRAS, a GTPase that regulates cell proliferation, frequently mutates in its codon 12 in multiple cancers, including our current Asian CDC cohort, where the patients were shown to have poor survival outcomes." (PMID 39122888, 2024). "The miRNAs dysregulated in PC target specific loci within the 3′UTR regions of KRAS, and some of them (rs8720, rs712, rs190084851, rs61764370 and rs9266) have been previously associated with different types of cancer." (PMID 39057123, 2024). "Different types of KRAS mutations, namely, G12A, G12S, Q61H, A146T, and K117N, are also associated with different types of cancer." (PMID 39056802, 2024). "Another recent study exploited a bypass of a late G1 glutamine (Gln)-dependent cell cycle checkpoint in cancer cells with KRAS mutations." (PMID 39272883, 2024). "In KRAS-mutated cancers, NRF2 can be increased, and a study in NSCLC showed how NRF2 can also regulate cell motility independently from EMT." (PMID 39594817, 2024). "Previous studies have reported that KRAS-mutated cancer cells contribute to an immunosuppressive environment by regulating immune cell behavior in PAAD56." (PMID 38684762, 2024).
cancer (continued). "KRAS peptide vaccines are an emerging approach aimed at eliciting an immune response against cancer cells that harbor KRAS mutations." (PMID 39337530, 2024). "Association of KRAS wild-type cancers (ETV6-NTRK3, TPR-NTRK1, SCLA5-NRG1, and ATP1B1-NRG1 fusions, IDH1 R132C mutation, and mismatch repair deficiency) with early-onset of disease." (PMID 39062863, 2024). "Prospective clinical trials are needed to fully determine the therapeutic opportunity of this CAR-T therapy in cancers harboring KRAS mutation, as well as determine the potential toxicities." (PMID 39456549, 2024). "Different types of KRAS mutations are found disproportionally in cancer types dependent on internal and external factors involved in oncogenesis." (PMID 39184150, 2024). "Mutations in KRAS codon 12 or 13 lead to cancer cell-intrinsic production of CXCL1, a chemokine which recruits MDSC and stimulates MDSC to produce tumor necrosis factor (TNF)." (PMID 39518557, 2024). "Of the oncogenic mutations in the RAS family, the KRAS locus is the most often affected with a relatively higher prevalence in about 30% of cancerous tumors, while the HRAS and NRAS locus mutations are present in a modest 8% and 3%, respectively." (PMID 39184150, 2024). "KRAS is the most frequently mutated oncogene in human cancer, contributing to approximately 25–30% of all cancer cases." (PMID 38397927, 2024). "Recent reports describe a significant prevalence of KRAS allelic imbalances or gene dosage changes in human cancers, including loss of the wild-type allele in KRAS mutant cancers." (PMID 38168062, 2024). "Regions that were significantly amplified in CS-like tumors held many genes known to be associated with cancer development, including KRAS, CDK4, and TERT." (PMID 38978078, 2024). "Given that G12D, G12V, and G12R KRAS mutations are more prevalent in KRAS-driven cancers like PDAC and CRC, there is a pressing need for effective therapies targeting these mutations." (PMID 39164274, 2024). "The prognostic significance of distinct KRAS activating mutations has been evaluated in different cancer contexts." (PMID 38261067, 2024). "KRAS mutations are one of the most prevalent oncogenic alterations in cancer, occurring in roughly 30% of all cancer types." (PMID 38727236, 2024). "KRAS is the most frequently mutated among the three isoforms; more than 85% of all cancers carry KRAS aberrations." (PMID 39749200, 2024). "While MYC expression in KRAS-mutant cancers was associated with sensitivity to a SUMOylation inhibitor, our limitations are that we used a biased approach to the analysis and were unable to define a cut-off value for MYC expression." (PMID 38992694, 2024). "Researchers found that after the initial KRAS mutation, cancer evolution requires an increased dose of oncogenes by amplifying mutated KRAS or other oncogenes such as YAP1 or NFKB2, through analyses of human PanIN lesions." (PMID 39839479, 2024). "The MYC, KIT and KRAS genes, all of which are implicated in various cancers, comprise G4-forming sequences within their promoters." (PMID 38407356, 2024). "Herein, we explored the cancer-associated fibroblasts (CAFs) secretome as a mediator of resistance to KRAS silencing." (PMID 39061234, 2024). "Kirsten Rat Sarcoma (KRAS) is a known oncogene and the most commonly mutated oncogene in all cancers." (PMID 39125664, 2024). "Single-point mutations in the Kirsten rat sarcoma (KRAS) viral proto-oncogene are the most common cause of human cancer." (PMID 38794122, 2024).
cancer (continued). "Further investigation of this phenomenon based on KRAS mutational types reveals that cancer cell lines harboring KRAS-G12C mutations tend to be more prone to FTis effects." (PMID 38278976, 2024). "Their review highlighted that IKKα has been associated with NFκB independent signalling in cancer, across KRAS mutant lung adenocarcinoma cells, basal cell carcinoma cells and breast cancer progenitors." (PMID 38975078, 2024). "In NSCLC, KRAS mutations are the most commonly detected alterations, found in approximately 30% of cancers." (PMID 38347643, 2024). "This suggests that out of all the BRAF polymorphisms, only BRAF V600E exerts a sufficiently strong cancer-promoting effect to act independently of KRAS mutations." (PMID 39456660, 2024). "We demonstrated that one copy of the endogenous KRAS.G12X oncogenic mutations causes cancer-relevant phenotypes, including an increase in cell proliferation and motility." (PMID 38796063, 2024). "KRAS activates effector proteins following their translocation to membrane and many diseases including a range of cancers result from gain‐of‐function mutations that persistently activate the kinase." (PMID 39673076, 2024). "The effectiveness of KRAS inhibitors in patients with other cancers with the G12C mutation in the KRAS gene compared to NSCLC patients seems less promising." (PMID 38397927, 2024). "KRAS proteins belong to a class of RAS proteins that participate in the RAS-GDP/GTP cycle, and somatic KRAS mutations are present in many different human cancer types." (PMID 38773970, 2024). "One frequent driver mutation in several cancers is known as the Kirsten rat sarcoma viral oncogene homolog (KRAS)." (PMID 39201772, 2024). "In another instance, corrections of kirsten rat sarcoma viral oncogene homolog (KRAS) G12D mutation, observed in many cancers, showed reduced cell growth compared to the wild-type cells with KRAS G12D mutations." (PMID 39726634, 2024). "KRAS mutation promotes the autonomous expression of type I cytokine receptor complexes (IL2r-IL4r and IL2r-IL13r1) in cancer cells, which can then bind to and take up cytokine growth signals (IL4 or IL13) released by Th2 cells in the microenvironment." (PMID 38481800, 2024). "Considering the significant advancements made in direct targeting drugs like sotorasib, it is anticipated that interest in cancers associated with KRAS mutations will remain steadfast." (PMID 38706597, 2024). "KRAS mutations comprise 77% of the RAS mutations in human cancer, making it the most frequently mutated RAS isoform." (PMID 38800401, 2024). "Oncogenic mutations in KRAS trigger persistent activation of KRAS-dependent pathways and have been detected across various cancer types." (PMID 38397135, 2024). "The constitutive activation of the RAS–ERK pathway as a result of KRAS mutations has led to the development of MEK inhibitors (MEKi) as a potential therapeutic strategy for the treatment of KRAS-mutant cancers." (PMID 38643157, 2024). "More recently, KRAS-targeted therapies not limited to KRAS G12C are being developed, potentially broadening the treatment landscape of KRAS-mutated cancers." (PMID 38756650, 2024). "MicroRNAs (miRNAs) play a crucial role in regulating gene expression at the mRNA level, including genes involved in the dysregulation of signaling pathways associated with cancer such as KRAS, JAK/STAT, PI3/AKT, Wnt/β-catenin and TGF-β." (PMID 39200178, 2024). "As a frequently mutated oncogenic driver protein, KRAS represents a compelling therapeutic target for cancer treatment." (PMID 38668053, 2024). "RAS mutations, including those affecting KRAS at codon 12 or 13, are frequently identified in many cancer types." (PMID 38627844, 2024). "A clinical phase I trial (NCT04916236) combining RMC-4630 and the ERK inhibitor LY3214996 for the treatment of KRAS-mutated cancer is ongoing." (PMID 38763973, 2024).
cancer (continued). "A study analyzing cancer specimens >13000 CRC pts also found a wider distribution of KRAS mutations in the MSI-H subset, including ~9% p.A146T and ~22% other missense structural variants." (PMID 39628993, 2024). "In this context, the inhibition of p44/42 MAPK activity achievable through MEK inhibition was explored as a potential strategy for cancers carrying KRAS mutations, drawing from their efficacy in treating BRAFV600-mutant melanoma." (PMID 38409090, 2024). "One noteworthy finding from the authors of this RAS Dialogue is the observation that the KRAS tissue permissiveness pattern observed in mice closely resembles the cancer-type specific KRAS mutation frequency observed in patients." (PMID 39455841, 2024). "KRAS mutations are found in approximately 30% of human cancers, making it one of the most common oncogenes." (PMID 38542866, 2024). "About 18% of all human cancers carry a mutation in the KRAS gene making it among the most sought-after anticancer targets." (PMID 38796063, 2024). "It is, therefore, plausible that in cancers harboring KRAS mutations, CAF-secreted factors can enhance the Hippo signaling pathway through the mediation of the TGF-β pathway." (PMID 39061234, 2024). "Existing KRASG12C inhibitors have narrow therapeutic windows and are only effective in a small proportion of cancer patients with KRAS mutation." (PMID 38763973, 2024). "PDAC is a deadly malignancy bearing distinct genetic alterations, the most common being those that result in cancer-causing versions of the KRAS gene." (PMID 38396679, 2024). "KRAS encodes a protein called K-Ras, which, when mutated, contributes to the development of cancer through pathways that promote growth, proliferation, and differentiation." (PMID 39720730, 2024). "This demonstrates that one copy of a KRAS.G12X oncogenic mutation is sufficient to cause a key cancer-related phenotype." (PMID 38796063, 2024). "Combined analysis of n = 1079 human cancer cell lines (> 25 lineages) showed that activating mutations in KRAS, NRAS and HRAS correlate significantly with increased c-RAF gene dependency vs. wild-type RAS." (PMID 38637546, 2024). "Mutations in KRAS oncogene are frequently detected in many cancers, including colorectal adenocarcinoma (CRC) and pancreatic ductal adenocarcinoma (PDAC)." (PMID 38168062, 2024). "Kirsten Ras (KRAS) mutation, one of the most prevalent alterations in human cancers, occurs in ≈25% of patients." (PMID 39254172, 2024). "KRAS is a GTPase mutated in about 25% of all human cancers and sits at the crux of molecular pathways driving tumorigenesis." (PMID 39355533, 2024). "Macropinocytosis is elevated in KRAS-mutated cancer cells to facilitate the bulk uptake of extracellular components." (PMID 38668053, 2024). "The preliminary results have shown that the combination of these drugs effectively kills cancer cells and shrinks tumors in several KRAS-mutated cancers in animals." (PMID 39000565, 2024). "Human cancer cell lines with KRAS mutations of G12C/S/R/V/D/A, G13C/D, and Q61H were obtained from ATCC and their genomic DNAs were prepared for use as test templates." (PMID 38938409, 2024). "According to statistical analyses, approximately 14% of all cancer patients harbor a mutant KRAS, making KRAS the most frequently mutated oncogene amongst all cancers." (PMID 38731892, 2024). "KRAS is the most frequently mutated oncogene in human cancers, thus representing an important therapeutic target." (PMID 39696697, 2024). "Although it has been suggested in the research literature, the connection between KRAS-mutated cancers and female gender is still a contentious issue." (PMID 39031216, 2024). "This study investigates the deliveryof the ascorbic acid derivative, palmitoyl ascorbate, to KRAS-mutatedcolorectal cancer cells in vitro." (PMID 39554410, 2024).